LINC00907 (long independently transcribed non-coding RNA 907)
Gene: Long non-coding RNA gene on chromosome 18 (42,159,087 to 42,734,297, forward strand). Ensembl gene ENSG00000267586.
Diseases named in the same sentence as LINC00907 in open-access papers:
LINC00907 is named in the same sentence as 8 diseases in open-access papers, as found by Europe PMC text mining. Sharing a sentence is not in itself a finding about the gene and the disease. The quoted sentences say what the papers report.
autism (1 paper, 2020). Persistent deficits in social interaction and communication and interaction as well as a markedly restricted repertoire of activity and interest as well as repetitive patterns of behavior. "We looked up the upstream and downstream locations of LINC00907 and found that the downstream Rit2 gene was associated with Parkinson's disease, schizophrenia, and autism." (PMID 33110425, 2020).
liver cancer (1 paper, 2023). An epithelial or non-epithelial malignant neoplasm that arises from the liver. "In addition, LINC00907 (logFC = −2.6057), CCN1 (logFC = −2.05925), GSTZ1 (logFC = −2.34197), and GSTM5 (logFC = −2.8954) were lowly expressed in liver cancer tissues." (PMID 36685007, 2023).
osteoporosis (1 paper, 2020). A condition of reduced bone mass, with decreased cortical thickness and a decrease in the number and size of the trabeculae of cancellous bone (but normal chemical composition), resulting in increased fracture incidence. "Therefore, the LINC00907 found in this study is significantly correlated with femoral neck bone mass, and these polymorphisms provide a basis for the follow-up function study in the pathophysiology of osteoporosis." (PMID 33110425, 2020).
steatosis (1 paper, 2024). Increased lipid within the cytoplasm of cells. "Histological examination using H&E, α-SMA, Masson, COL1A1 and FASN staining revealed that the degree of hepatic steatosis and hepatocellular ballooning in linc00907 knockdown mice was less severe than that in the control group, and lipid accumulation was also less pronounced." (PMID 38613803, 2024).
cancer (1 paper, 2024). A tumor composed of atypical neoplastic, often pleomorphic cells that invade other tissues. "The more cancer-specific lincRNAs are LINC00470, LINC00668, LINC00907, LINC01254, LINC01415, LINC01478, and LINC01539." (PMID 38540157, 2024).
LINC00907 also shares sentences with these, for which no sentence is quoted: Parkinson disease (1 paper); schizophrenia (1); tumor (1).